MTOR (mechanistic target of rapamycin kinase)
Diseases named in the same sentence as MTOR in open-access papers (continued):
Sharing a sentence is not in itself a finding about the gene and the disease.
cancer (continued). "Disturbances in the PI3K/Akt/mTOR pathway play a central role in cancer, the most common deregulations being a loss of PTEN, amplification of the PIK3CA or AKT gene locus and PIK3CA mutations." (PMID 35780223, 2022). "In total, our pooled analysis identified 22 eligible case-control studies comprising 14,747 cancer patients and 16,399 controls on the two mTOR variants." (PMID 35082928, 2022). "Activating mutations of proto-oncogenes such as EGFR, PI3K, and AKT as well as inactivating mutations of tumor suppressor PTEN or TSC1/2 causes the activation of the mTOR signaling pathway in a wide range of cancers." (PMID 35805935, 2022). "Genetic polymorphisms in mammalian target of rapamycin (mTOR) signaling axis can influence the susceptibility of cancer." (PMID 35082928, 2022). "Cancer is caused by defects in growth control, therefore it's unsurprising that mTOR also plays a role in its pathogenesis." (PMID 35370701, 2022). "A large body of studies has reported that dysregulations in PI3K/mTOR are associated with the development of various types of cancer in humans." (PMID 36109789, 2022). "AKT/mTOR signaling pathway has been associated with many types of cancer, as all of its components are often deregulated." (PMID 34614271, 2022). "The progression of cancer is associated with several signaling cascades, and mammalian target of rapamycin (mTOR) is one them." (PMID 35795855, 2022). "Leucine, one of the essential amino acids, has recently been found to be closely associated with cancer, which activate mTOR signaling pathway." (PMID 35008399, 2022). "The mTOR is frequently deregulated in tumorigenesis, activating somatic mutations of mTOR, which were recently identified in several types of cancer, and hence mTOR is therapeutically targeted." (PMID 35372388, 2022). "This notion is further supported by the reports of increased sensitivity to DNA damage-inducing therapies in cancer patients with mTOR activation caused by germline and/or somatic mutations of TSC1/238–41." (PMID 36396656, 2022). "Using Memorial Sloan-Kettering Cancer Center dataset (MSKCC), we extracted mTOR pathway gene mutations for stepwise Cox regression in 1661 cancer patients received ICI." (PMID 35642038, 2022). "Dysregulation of mTOR signaling is associated with the initiation and progression of cancer, and overactivated mTORC1 signaling has been demonstrated to promote malignant behaviors of cancer cells." (PMID 36060239, 2022). "In summary, the present study summarized all eligible data for the genetic relationship between the mTOR variants rs2295080 T/G or rs1883965 G/A and susceptibility to different cancers." (PMID 35082928, 2022). "The Ser/Thr kinase mTOR cascade is commonly up-regulated in cancer due to loss of the tumor suppressor PTEN, as in U-87 MG." (PMID 36552831, 2022). "It is also observed that many diseases like mitochondrial dysfunction, auto-immunity, and cancer affect these pathways, causing uncontrolled stimulation of mTOR and leading to tau protein hyperphosphorylation." (PMID 36618946, 2022). "One prospect is- based on these findings a guideline can be prepared to detail all the deleterious SNPs within mTOR which can potentially increase the risk of cancers and other disease susceptibilities." (PMID 35788771, 2022). "The PI3K/AKT/mTOR signaling pathway is crucial in regulating tissue homeostasis, and its dysregulation can cause various pathological conditions including cancers." (PMID 35017531, 2022). "The mTOR mutation was found in a wide variety of malignant tumors, including lung, renal cell, endometrium, colorectal and squamous carcinoma." (PMID 36539659, 2022). "Sirolimus and its variants are powerful and selective mTOR inhibitors that have gotten a lot of interest as possible anti-cancer drugs." (PMID 36109789, 2022). "The PI3K/AKT/mTOR signaling pathway is overactive in many cancers and is strongly linked to cell proliferation, cell cycle, autophagy, and apoptosis." (PMID 35529455, 2022).
cancer (continued). "The PI3K/AKT/mTOR signaling pathway has been linked to radiotherapy resistance, and the effect of inhibitors of this pathway as cancer radiosensitization is worth investigating." (PMID 36555391, 2022). "Overexpression of human GOLPH3 correlates with poor prognosis in several cancer types and is associated with enhanced signaling downstream of mTOR (mechanistic target of rapamycin)." (PMID 36435842, 2022). "These PKD2-mediated actions cause GOLPH3-induced activation of the PI3K/AKT/mTOR signaling pathway, thus promoting cancer cell proliferation." (PMID 35805075, 2022). "The autophagic process is controlled by different proteins, including the mammalian target of rapamycin (mTOR), which is associated with cell proliferation and cancer progression." (PMID 35070357, 2022). "Surprisingly, this computational analysis allowed us to identify in silico various critical players implicated in cancer processes, such as mTOR, BLM, MET, AMPK, and p130 (RBL2), as novel SMYD3 interactors." (PMID 35495117, 2022). "Dysfunctional EGFR, KRAS, and mammalian/mechanistic target of rapamycin (mTOR) pathway also cause metabolic reprogramming, leading to the progression of numerous cancers, including GC." (PMID 36145507, 2022). "The current study sought to identify all eligible case-control studies to comprehensively assess the association between mTOR variants rs2295080 T/G or rs1883965 G/A and susceptibility to cancer." (PMID 35082928, 2022). "Previous studies have evaluated the association of genetic variants of the mTOR gene with the susceptibility to cancer." (PMID 35082928, 2022). "A number of recurrent cancer hotspot MTOR variants were commonly found in these studies, including c.6644C>T (p.Ser2215Phe), c.6644C>A (p.Ser2215Tyr) and c.4379T>C (p.Leu1460Pro), all of which were previously found to confer mTOR pathway hyperactivation." (PMID 35163267, 2022). "The third generation of mTOR inhibitors is a more recent family of inhibitors that are developed to be active against drug resistance in cancer cells with mTOR FRB/kinase domain mutations." (PMID 36109789, 2022). "Several previous publications have assessed the association of mTOR variants rs2295080 T/G or rs1883965 G/A and susceptibility to cancer." (PMID 35082928, 2022). "Accordingly, this review presents an overview of recent developments associated with the mTOR signaling pathway and its molecular involvement in various human cancer types." (PMID 36428613, 2022). "Although the TCGA study showed that the genomic alteration of the PI3K/AKT/mTOR pathway occurred in 42% of invasive bladder cancer cases, there were few cancer-associated mutations that were directly linked to the MTOR gene itself." (PMID 35326708, 2022). "Mutations in MTOR have been shown to alter the sensitivity to rapalog treatment in several cancer types." (PMID 35883111, 2022). "PI3K/AKT/mTOR pathway activation has been linked to cell proliferation, progression, angiogenesis, therapy resistance, and invasion in various forms of cancer malignancy." (PMID 35682652, 2022). "The dysregulation of the mTOR signaling pathway has also been linked with cancer, inflammation, diabetes, and neurological diseases." (PMID 35831271, 2022). "To further explore the molecular mechanisms of LDOC1, we examined the expression of essential proteins in the AKT/mTOR signaling pathway implicated in cancer cell viability and proliferation." (PMID 35957693, 2022). "The activation of PI3K/AKT/mTOR pathway is the primary mechanism causing cancer cells to develop radiation resistance." (PMID 36555391, 2022). "Aberrant activation of the PI3K/AKT/mTOR (Mammalian target of rapamycin) pathway has been associated with many human cancer types." (PMID 36015192, 2022). "In summary, the activation of the PI3K/AKT/mTOR signal pathway has been linked to radiotherapy resistance, and the effect of inhibitors of this pathway as a type of cancer radiosensitization is worth investigating." (PMID 36555391, 2022).
cancer (continued). "In fact, 70% of all known cancers have been shown to be associated with aberrant hyperactivation of mTOR, which promotes cellular proliferation and delays the apoptosis of tumor cells." (PMID 35831271, 2022). "To investigate the role of autophagy, a cellular process associated with cancer stemness, in the mTOR-related increase in EC cell stemness, we assessed the expression of p-mTOR and LC-3II/LC-3I ratio, as an index for autophagosome formation." (PMID 35406578, 2022). "AMPK signaling is linked with catabolism and cell cycle progression, mTOR signaling supports cancer metabolic flexibility and cancer cell survival, and the electron transport chain yields ATP and reactive oxygen species (ROS), which act as signaling molecules." (PMID 35054787, 2022). "PIK3CA is not only one of the PI3K/AKT/mTOR pathway members but is also the most frequently mutated oncogene in human cancers." (PMID 36333792, 2022). "In third-generation inhibitor RapaLINK, rapamycin and an ATP analog are chemically linked together, so RapaLINK has the performance of both rapamycin and ATP analog, reducing drug-resistant problems in mTOR mutated cancers." (PMID 35740927, 2022). "Together, these data demonstrate that NPC1 silencing acts on the mTOR pathway in association with decreased cancer cell viability, proliferation, and invasive capacity." (PMID 35884604, 2022). "Arginine is one of three amino acids that can activate mTOR, and some cancer cells are deficient in arginine synthesis." (PMID 34697412, 2022). "The signalling pathways upstream and downstream of the mTOR are often dysregulated in cancer, and its functions depend on the mTOR-associated complexes’ activity, such as mTORC1 and mTORC2." (PMID 36615513, 2022). "We also tried to show aging progression by hyperactivation of mTOR by the point mutation S2215Y, identified in the human cancer genome database." (PMID 36474295, 2022). "Activation of PIK3CA mutations in cancer predominantly leads to the dysregulation of the PI3K/AKT/mTOR pathway." (PMID 36333792, 2022). "Collectively, mTOR pathway mutations are obviously involved in cancer immunity, and affect the sensitivity to ICI treatment." (PMID 35642038, 2022). "Our analysis does indicate a significant association of mTOR rs2295080 T/G and rs1883965 G/A polymorphism with the risk of cancer." (PMID 35082928, 2022). "Upregulated mTOR signaling activities and hyperactive MTOR mutations have been reported in various types of cancer." (PMID 35831271, 2022). "The majority of patients harboured three or more actionable mutations affecting key cancer related regulatory networks including the PI3K/AKT/MTOR and RAS/RAF/MEK/MAPK signalling pathways, DNA-damage repair pathways and cell cycle checkpoints." (PMID 35324914, 2022). "In the present study, we have reported that mutations in mTOR pathway, a classical modulator in cancer cell metabolism and cancer malignancy, were predictable for ICI treatment outcome." (PMID 35642038, 2022). "The genetic variants identified affect many key cancer-related regulatory networks including the PI3K/AKT/MTOR, RAS/RAF/MEK/MAPK, JAK/STAT, PLC/PKC signalling pathways, DNA damage repair (DDR) pathways and cell cycle and immune checkpoints." (PMID 35324914, 2022). "The PI3K/AKT/mTOR pathway is tightly implicated in tumorigenesis, cancer cell proliferation, and RT-resistance." (PMID 35485300, 2022). "Among many cancers, the development of head and neck cancer is the consequence of genetic changes that deregulate mTOR signaling causing a metabolic rearrangement." (PMID 36428613, 2022). "The Akt/mTOR pathway is one of the most involved pathways in cell proliferation associated with cancer." (PMID 35159040, 2022). "Second, we used fewer rapamycin (mTOR) inhibitors, which have potential advantages in virus-associated posttransplant malignancies as well as anti-cancer properties." (PMID 35626329, 2022).
cancer (continued). "The present study is aimed at comprehensively investigating the association between mTOR polymorphisms and susceptibility to cancer." (PMID 35082928, 2022). "Another study using the Catalogue of Somatic Mutations in Cancer (COSMIC) database (up to February 2019) revealed that the somatic mutation of MTOR was observed in 5.1% of urinary tract cancers (58/1138) whereas protein overexpression was 6.6% (27/408)." (PMID 35326708, 2022). "Pathological conditions, such as neurological diseases, cancer, and metabolic problems, have been associated with dysfunctions in the mTOR signaling." (PMID 36478736, 2022). "Persistent mTOR activity is associated with drug resistance in cancer treatments, including Mitogen-activated protein kinase kinase (MEK) inhibitors." (PMID 36267578, 2022). "The PI3K/AKT/mTOR pathway, which plays essential roles in cell proliferation and survival is frequently deregulated in cancer, in particular due to loss of PTEN, as in the case of H1299." (PMID 34596822, 2022). "mTOR/AKT is activated in numerous cancers, generally through mutations in upstream regulators, including PTEN and PIK3CA." (PMID 35884604, 2022). "Tumor suppressive miR-99b-5p has been implicated in regulating PI3K/AKT/mTOR signaling in a variety of types of cancer." (PMID 36077039, 2022). "Given that the downstream mTOR pathway inhibition can be associated with (Z)-BP-inactivated receptor tyrosine kinase including Axl, several cancer pathways are blocked, and a synergistic effect with TMZ is then achieved." (PMID 35646111, 2022). "The DDIT4 gene encodes a protein whose main action is to inhibit mTOR under stress conditions, whilst several in vitro studies indicated that its expression favors cancer progression." (PMID 35754835, 2022). "Enhanced activity of the phosphoinositide 3-kinase (PI3K)/AKT/mechanistic target of rapamycin (mTOR) signaling pathway is among the most frequently observed changes in cancer and is associated with tumor invasiveness, survival, and proliferation." (PMID 35440108, 2022). "Despite extensive investigation of the role of miRNAs in mTOR or Stat3 activation, there is limited research on the role of miRNAs in the pathology of cancer-associated fibrosis using animal models." (PMID 35211358, 2022). "Loss of PTEN induces radioresistance in cancer cells by the downregulation of radiation-induced autophagic cell death which has been observed to be overcome by treating the cells with mTOR inhibitors." (PMID 36172166, 2022). "It has been reported that the components of the upstream and downstream signaling of mTOR pathway are often changed to promote tumor progression in various types of cancers, such as amplification of PI3K, loss of PTEN function and overexpression of AKT." (PMID 36676047, 2022). "The current study sought to identify all eligible case-control studies to comprehensively assess the association between mTOR variants rs2295080 T/G or rs1883965 G/A and susceptibility to a variety of cancers." (PMID 35082928, 2022). "Literature data about miR-33a indicate that it participates in nine signaling pathways that are associated with cancer, one of which is mTOR." (PMID 36430972, 2022). "Most of the survival signaling molecules including PI3K, PDK1, AKT and mTOR have been associated with lipid rafts in cancer cells." (PMID 35260193, 2022). "A highly soluble compound over a wide pH range, Samotolisib is an ATP-competitive inhibitor that effectively inhibits PI3K, mTOR, and DNA-PK, as well as inhibiting the viability of cancer cells and causing cell cycle effects." (PMID 35614940, 2022). "Hyperactive mutation of PI3K/AKT/mTOR signaling can suppress cancer cells ferroptosis by upregulating the SREBP1-mediated lipogenesis." (PMID 36061427, 2022).
cancer (continued). "PTEN is a tumor suppressor gene that can negatively regulate the PI3K/AKT/mTOR pathway and is one of the most common mutated genes in cancer." (PMID 35402264, 2022). "Aberrant mutations in the PI3K/AKT/mTOR signalling pathway are widely observed in human malignant tumours." (PMID 35165269, 2022). "Although further investigations will better clarify the relationship between NRF2 and mTOR, it has been reported that mutations in the Nrf2 gene increase the susceptibility of cancer cells to the cytotoxic effects of mTOR inhibitors." (PMID 36614036, 2022). "The mTOR is one of the key members in pI3K-AKT-mTOR pathway that have been implicated in the progress of several carcinomas." (PMID 36034650, 2022). "The ILK/AKT and mTOR signaling pathway regulates various aspects of cell development and is also implicated in the progression of human carcinomas." (PMID 35676936, 2022). "Previous studies have also linked overexpression or mutation of core genes in the mTOR pathway to the occurrence, invasion, and prognosis of many carcinomas." (PMID 35082928, 2022). "The aberrant regulation of the mTOR signal transduction pathway has been implicated in a wide spectrum of carcinomas." (PMID 35082928, 2022). "A previous study showed that single nucleotide polymorphisms (SNPs) in the PI3K/AKT/mTOR pathway are connected to the distant metastasis of carcinomas." (PMID 36539659, 2022). "Loss of rDNA in mouse cancer lines is associated with vulnerability to DNA damage and activation of the mTOR pathway, which promotes cell growth and division." (PMID 34257925, 2021). "First, mutations in the mTOR gene lead to constitutive activation of mTOR, which has been reported in a few human cancers." (PMID 35250965, 2021). "The AKT and mTOR are also predominantly associated with Cancer as well as with each other in the network shown." (PMID 34200663, 2021). "The MTOR missense/activating mutations identified in other cancers are considered biomarkers for therapy with mTOR pathway inhibitors." (PMID 34900699, 2021). "Although there are no data directly linking PPARG with AML, it is worth mentioning that the protein is implicated in the TGF-beta and mTOR signaling pathways, both associated with cancer development." (PMID 34502231, 2021). "Activated PI3K signaling also leads to downstream activation of the protein kinase B (also known as Akt) and mechanistic target of rapamycin (mTOR) pathways, both of which are implicated in the progression of various cancers including BC." (PMID 34716900, 2021). "Phytoestrogens restrict PI3K/Akt/mTOR signaling pathways and this mechanism has been implicated in their ability to induce autophagy and kill cancer cells." (PMID 33768214, 2021). "Collectively, these findings illuminate the potential for repurposing drugs that are involved with inhibition of the PI3K/AKT/mTOR signaling pathway and cancer treatment as potential therapeutics for PML, caused by this neuroinvasive virus." (PMID 34831441, 2021). "Overactivation of AKT/mTOR is associated with carcinogenesis and has become a potential molecular therapeutic target in cancer therapy." (PMID 34527062, 2021). "The purpose of this review was to analyze the mTOR pathway in pluripotent cells in order to define the hypothetical mTOR pathway profile underlying cell dormancy in common, with subsequent application of it in the field of cancer research." (PMID 34832087, 2021). "In NSCLC depletion or mutation of multiple genes (PTEN, PI3KCA, RTK, etc.)shall cause dysregulation and overactivation of mammalian target of rapamycin (mTOR), thus promoting tumorigenesis and cancer progression." (PMID 34326320, 2021).